COG6 (component of oligomeric golgi complex 6)
Description:
Required for normal Golgi function.
Synonyms: KIAA1134; COD2; CDG2L; SHNS
Tractability: Antibody: UniProt places it where antibodies can reach, with medium confidence. PROTAC: ubiquitination databases record sites on it; its protein half-life has been measured.
Target class: Other cytosolic protein
Gene: Protein-coding gene on chromosome 13 (39,655,627 to 39,791,666, forward strand). Ensembl gene ENSG00000133103.
Subcellular location: Golgi apparatus membrane
Subcellular location (Human Protein Atlas): Golgi apparatus; Nuclear speckles
Pathways (Reactome):
Vesicle-mediated transport: COPI-mediated anterograde transport; Intra-Golgi traffic; Retrograde transport at the Trans-Golgi-Network
Gene Ontology:
Molecular function: protein binding
Biological process: Golgi organization; retrograde transport, vesicle recycling within Golgi; intra-Golgi vesicle-mediated transport
Cellular component: Golgi transport complex; Golgi membrane; trans-Golgi network membrane
Genetic constraint (gnomAD): Loss-of-function variants: 26 observed, 34.14 expected, observed/expected ratio (o/e) 0.76, 90% interval 0.56 to 1.06. The upper end of that interval is the gene's LOEUF score, 1.06, which puts it in group 4 of 6, group 1 being the genes least tolerant of losing a copy. Missense variants: 435 observed, 446.92 expected, observed/expected ratio (o/e) 0.97, 90% interval 0.9 to 1.05. Synonymous variants: 180 observed, 166.07 expected, observed/expected ratio (o/e) 1.08, 90% interval 0.96 to 1.23.
Gene-disease validity (ClinGen):
ClinGen rates the evidence that COG6 causes each of these diseases.
COG6-congenital disorder of glycosylation (autosomal recessive): Definitive.
Homologues: Orthologues: chimpanzee COG6 (99% identical), macaque COG6 (98% identical), rabbit COG6 (95% identical), dog COG6 (95% identical), pig COG6 (95% identical), guinea pig COG6 (92% identical), mouse Cog6 (91% identical), rat Cog6 (90% identical), tropical clawed frog cog6 (85% identical), zebrafish cog6 (80% identical), Drosophila melanogaster Cog6 (40% identical), Caenorhabditis elegans cogc-6 (22% identical).
Diseases named in the same sentence as COG6 in open-access papers:
COG6 is named in the same sentence as 29 diseases in open-access papers, as found by Europe PMC text mining. Sharing a sentence is not in itself a finding about the gene and the disease. The quoted sentences say what the papers report.
microcephaly (6 papers, 2019 to 2025). A congenital or acquired developmental disorder in which the circumference of the head is smaller than normal for the person's age and sex. "Biallelic mutations of COG6 lead to congenital disorders of glycosylation, with features such as liver abnormality, microcephaly, and developmental disability." (PMID 36115840, 2022). "In this study, we describe a Chinese girl with developmental delay, microcephaly, and abnormal liver function carrying two novel compound‐heterozygous mutations in COG6 gene (OMIM 606977) inherited from her parents, respectively." (PMID 34331832, 2021). "We identified two compound heterozygous variants in COG6 gene in a patient with developmental delay, facial dysmorphism, microcephaly, recurrent infection, and hypohidrosis." (PMID 34331832, 2021). "We summarized the clinical manifestations of patients reported by reviewing the literatures and found that microcephaly is a consistent clinical hallmark of COG6‐CDG, which could be found at birth or in later development." (PMID 34331832, 2021). "Studies have shown that patients with COG6 deficiency present with developmental delay, growth retardation, and microcephaly, suggesting that COG6 is critical for normal somatic and neural development." (PMID 41514807, 2025). "A very rare subtype, COG6-CDG, is caused by deficiency of subunit 6 of the conserved oligomeric Golgi complex and is usually characterized by growth retardation, developmental delay, microcephaly, liver and gastrointestinal disease, joint contractures and episodic fever." (PMID 32905044, 2020).
rheumatoid arthritis (3 papers, 2016 to 2024). A chronic, systemic autoimmune disorder characterized by inflammation in the synovial membranes and articular surfaces. "Other loci containing alleles robustly associated with higher eosinophil count and increased risk of rheumatoid arthritis were COG6, SPRED2, RUNX1, and the highly pleiotropic ATXN2/SH2B3/BRAP region." (PMID 27863252, 2016). "Interestingly, single nucleotide polymorphisms of the COG6 gene have been recently shown as shared risk locus for rheumatoid arthritis and systemic lupus erythematosus." (PMID 29510755, 2018).
Shaheen syndrome (2 papers, 2020 to 2022). "Variants linked to residual COG6 activity are likely to cause milder phenotypes, as in the case of the deep intronic splice site variant reported in a small subgroup of patients with Shaheen syndrome." (PMID 35068072, 2022). "Transferrin glycosylation analyses showed a type 2 pattern in agreement with defective Golgi trafficking in COG6‐CDG except in Shaheen syndrome." (PMID 35068072, 2022).
anaplastic astrocytoma (1 paper, 2021). "In detail, one patient collected tumor specimens in all stages of MT in the present cohort.PRKCQ,PPIF,NRP1,MEFV,GGT1,FAN1, andBTKmutations were found in both DA and anaplastic astrocytoma, whereas mutations ofTBC1D19,ESRRA,DIAPH2,COG6, andCBWD3occurred in HGA." (PMID 34430964, 2021).
arthrogryposis (1 paper, 2025). A rare, non-progressive congenital disorder characterized by multiple joint contractures which are present at birth. "A targeted, comprehensive panel for arthrogryposis and skeletal dysplasias revealed a homozygous variant c.906_907delinsA, p.(His302GlnfsTer4) in exon 9 in the COG6 gene (NM_020751.3) located on chromosome 13q14.11, inherited from both the patient's father and mother." (PMID 41362306, 2025).
Autoimmunity (1 paper, 2025). The occurrence of an immune reaction against the organism's own cells or tissues. "As noted, this locus is near the COG6 gene and the TNFSF11 gene, among others, which have been associated with autoimmunity." (PMID 41425598, 2025).
Bardet-Biedl syndrome 12 (1 paper, 2021). Any Bardet-Biedl syndrome in which the cause of the disease is a mutation in the BBS12 gene. "These variations were present in genes BBS12, STIL, COG6 and PIEZO1.A mutation in BBS12 causes Bardet-Biedl syndrome 12 (OMIM #615989)." (PMID 33772059, 2021).
cholestasis (1 paper, 2017). Impairment of the bile flow caused by obstruction within the liver, or outside the liver in the bile duct system. "In CDG presenting with cholestasis (such as ALG8-CDG, COG6-CDG, COG7-CDG, CCDC115-CDG and ATP6AP1-CDG), nutritional interventions such as in other causes of cholestasis can be necessary." (PMID 29112118, 2017).
diabetes (1 paper, 2022). "ATF3, ADP ribosylation factor-4 (ARF4), cAMP response element binding protein-3 (CREB3), and Component Of Oligomeric Golgi Complex-6 (COG6) were identified as potential Golgi regulatory factors that are dysregulated in both major forms of diabetes." (PMID 35204835, 2022).
disorder of glycosylation (1 paper, 2023). A disease that has its basis in the disruption of glycosylation. "Here, we present the first two Swedish cases of Conserved Oligomeric Golgi complex subunit 6‐congenital disorders of glycosylation (COG6‐CDG)." (PMID 36636598, 2023).
Dry skin (1 paper, 2020). Skin characterized by the lack of natural or normal moisture. "Skin manifestations such as dry skin and hyperkeratosis have been reported in only five out of the 21 reported COG6-CDG cases so far, including two patients with the c.511C>T variant in COG6 but with milder ectodermal symptoms." (PMID 32905044, 2020).
psoriasis (1 paper, 2015). An autoimmune condition characterized by red, well-delineated plaques with silvery scales that are usually on the extensor surfaces and scalp. "The next candidate genes, COG6 and LHFP, were found to be associated with susceptibility to psoriasis." (PMID 25585689, 2015).
infection (4 papers, 2020 to 2024). The state of being infected such as from the introduction of a foreign agent such as serum, vaccine, antigenic substance or organism. "The negative impact on BoHV-1 replication associated with the loss of COG6 expression was further evidenced by delayed production of the VP26-GFP protein after high or low MOI infection of COG6-/- KO cells with BoHV-1 VP26-GFP virus compared to the Cas9+/+ control cells." (PMID 38400072, 2024). "These negative results, obtained after single cycle infections from COG6 and COG7 KOs, are contrary to the significant reductions of virus titers collected from the same cells after multi-cycle infections." (PMID 38400072, 2024).
tumor (2 papers, 2021). "mRNA expression levels of COG subtypes depended on the tumour grade, especially COG4, COG5, COG6, COG7, and COG8." (PMID 34539936, 2021). "Similarly, high mRNA expression of 5 of all COG isoforms (COG2, COG3, COG5, COG6, COG7, and COG8) was also correlated with favourable OS of KIRC patients with tumour grade 2, grade 3, and grade 4, while patients with low mRNA expression of COG4 showed higher survival rate." (PMID 34539936, 2021).
cancer (1 paper, 2023). A tumor composed of atypical neoplastic, often pleomorphic cells that invade other tissues. "It has been reported that COG6 depletion can cause instability of the other lobe B COG subunits in both COG6‐CDG patients and other cancer cell lines." (PMID 36636598, 2023).
COG6 also shares sentences with these, for which no sentence is quoted: developmental delay (3 papers); gastrointestinal disease (2); Cerebellar atrophy (1); Failure to thrive (1); Hyperkeratosis (1); hypohidrosis (1); Intellectual disability (1); juvenile retinoschisis (1); keratosis pilaris (1); lipoma (1); neurologic disease (1); schizophrenia (1); skeletal dysplasia (1); systemic lupus erythematosus (1).